LEP (leptin)
Diseases named in the same sentence as LEP in open-access papers (continued):
Sharing a sentence is not in itself a finding about the gene and the disease.
heart disease (15 papers, 2009 to 2025). "Concerning leptin, an increase of serum leptin concentration has been proposed in humans as a risk factor for cardiac disease." (PMID 35878343, 2022). "Leptin has been linked to increased levels of CRP in blood vessels, which is associated with a higher risk of heart disease, and there is a link between leptin and CRP." (PMID 40871683, 2025). "Researchers believe that leptin can be used as a target for the treatment of heart disease and, in recent years, they have searched for leptin antagonists or inhibitors of leptin synthesis." (PMID 40417460, 2025). "Leptin increases inhibition of protein degradation and production of muscle cells, also leptin suppressed heart muscle inflammation and this is useful in the protection and treatment of heart disease." (PMID 25914798, 2015). "There are questions remaining about the fact that only those patients with possible or doubtless diagnosis of ischaemic heart disease showed decreases in plasma leptin levels immediately after effort." (PMID 24616817, 2014). "There are no studies regarding the relationship between short-term effort and fluctuations of plasma leptin levels in patients suffering from ischaemic heart disease." (PMID 24616817, 2014). "Research indicates that individuals with heart disease may experience altered leptin and ghrelin levels, leading to an increased appetite for energy-dense foods." (PMID 41370490, 2025). "High blood levels of leptin have been used to predict the severity of heart diseases, including HF." (PMID 40417460, 2025). "Attenuated leptin signaling may be involved in hypoxia-induced cardiac injury, offering new clues for the prevention and treatment of cardiac diseases under high-altitude hypoxia." (PMID 38702334, 2024). "Also, lower levels of circulating leptin were found immediately after exercise testing in patients with certain or probable diagnosis of ischaemic heart disease (groups 1 and 3)." (PMID 24616817, 2014). "Thus, the role of leptin on heart disease is still controversial both in experimental and human studies." (PMID 23270329, 2012). "This prospective cohort study suggests the protective effect of leptin for heart disease." (PMID 23270329, 2012). "Similarly, myocardial leptin expression was increased in dogs with CHF due to the acquired heart disease compared to dogs with congenital abnormalities and healthy dogs, with higher expression in dogs undergoing advanced CHF compared to those in the early and intermediate stages of CHF." (PMID 35878343, 2022). "However, only few studies investigated the role of leptin in canine cardiac diseases." (PMID 31091785, 2019). "They reported that higher leptin was associated with lower LV mass, wall thickness, and LAD size in individuals older than 70 years of age, and general community-based patients without known cardiac disease." (PMID 31703113, 2019).
liver (12 papers, 2013 to 2025). "Visfatin, such as leptin, is another adipokine that supports colorectal carcinogenesis through different signaling pathways activation, such as ERK1/2, p38 MAPK, PI3K/mTOR, JNK, and JAK/STAT, which promote cell proliferation and metastasis." (PMID 37760840, 2023). "Recently, leptin was shown to contribute to mucin production and the formation of gastrointestinal neoplasms by modulating mTOR-, STAT3-, and ERK-dependent pathways in addition to PKC-, PI3K-, and MAPK-dependent pathways." (PMID 26839577, 2016). "Animal studies using high fat diet-induced fatty liver rats demonstrated that JZG may have an effort on leptin pathway." (PMID 24369486, 2013). "Leptin binds to its specific receptor, OB-R, and induces IL-6, MMPs, and TGF-β overexpression by c-Jun, Akt, and JAK/STAT3 signaling pathways activation, which promote colorectal carcinogenesis." (PMID 37760840, 2023). "Acute exercise could also indirectly activate the liver leptin-AMPK-ACC signaling pathway and increase insulin sensitivity, but it should be noted that irreversible liver lipid disorders are induced by a high fat diet." (PMID 24455748, 2013).
adenocarcinoma (11 papers, 2012 to 2024). A common cancer characterized by the presence of malignant glandular cells. "To check the effect of Sam68 down-regulation on insulin and leptin-dependent phosphorylation of the main proteins of these signalling pathways, we used adenocarcinoma MCF7 cells as it was shown to have better response to insulin and leptin." (PMID 27415018, 2016). "We have now tested this possible implication of Sam68 in leptin and insulin signalling in adenocarcinoma cells by studying Tyr-phosphorylation mediated by these hormones." (PMID 27415018, 2016). "The mean serum leptin level was found to be significantly higher in patients with adenocarcinoma than in those with the squamous cell subtype, suggesting that measuring serum leptin could be a noninvasive method for pathological diagnosis." (PMID 33799880, 2021). "In vitro, leptin induces the migration of AGS cell (adenocarninoma) and MKN-45 cell (poorly differentiated adenocarcinoma) by upregulating ICAM-1 expression, hence suggesting that leptin can activate or modulate a variety of signaling cascades." (PMID 31141984, 2019). "Our data has also shown that leptin/LEPR signaling enhanced proliferation in the HEY3 and SKOV3 adenocarcinoma cell lines also via JAK2/STAT3." (PMID 29212170, 2017). "ACI, PAP and LEP adenocarcinomas together with one sample without pathological information were defined as non-solid-predominant (non-SOL, n = 81)." (PMID 38182978, 2024). "In order to check the effect of leptin and insulin on Sam68 expression in the three adenocarcinoma cell lines, they were independently incubated in the absence of serum with and without leptin or insulin (1 nM) for 24 h." (PMID 27415018, 2016). "In addition, Leptin, AMPK, and other factors become targets to improve fatigue after chemotherapy in adenocarcinoma patients, thus providing a new theoretical basis for acupuncture therapy to improve fatigue after chemotherapy in adenocarcinoma patients." (PMID 37542585, 2023).
endocrine disorders (9 papers, 2018 to 2025). "This situation may be a major cause of endocrine disorders, including secretion leptin." (PMID 33430445, 2021). "Sleep loss may lead to metabolic and endocrine disorders, including reduced glucose tolerance and changes in appetite-regulating hormones, such as the ghrelin, a hunger-promoting hormone which increases with sleep restriction, while leptin is the hormone which contributes to satiety is reduced." (PMID 29568522, 2018). "Other mechanisms include damage to the vascular endothelium due to oxidative stress, altered coagulation status due to fluctuations in the expression levels of coagulation factors, and imbalance in the levels of insulin and leptin secretion due to endocrine disorders." (PMID 39464793, 2024).
genetic disorders (8 papers, 2014 to 2025). "The molecular diagnosis of this rare genetic disorder is important due to the possibility of treatment with recombinant leptin." (PMID 31067764, 2019). "Absolute deficiency of leptin is also a clinical feature of congenital leptin deficiency (CLD), an ultrarare genetic disorder associated with biallelic pathogenic variants in the leptin gene and characterized by extreme hyperphagia and several neuroendocrine defects." (PMID 40469440, 2025). "We thus performed detailed novel measurements and analyses of samples and data from our clinical trials biobank to investigate leptin effects on mechanisms of weight regulation in lean normo- and mildly hypo-leptinemic individuals without genetic disorders." (PMID 33051459, 2020). "We observed similar correlations between BMI and BMI metabolomic score within the different genetic disorders studied; there was no consistent change in the metabolomic BMI score after leptin treatment (P = 0.69; paired Wilcoxon signed rank)." (PMID 32392278, 2020).
respiratory diseases (8 papers, 2010 to 2025). "Similarly, LEP receptors are expressed in various respiratory cells, including airway epithelial cells and smooth muscle cells, as well as in the lung tissue, indicating a strong association between LEP and respiratory diseases." (PMID 40337271, 2025). "In this context, leptin monitoring is suggested in obese subjects under control as an indicator of possible respiratory disorders." (PMID 40870537, 2025). "The contribution that leptin makes to glucocorticoid-induced lung maturation and the extent to which respiratory disorders in neonatal and adult life have their origins in leptin dysfunction before birth remains to be established." (PMID 26287800, 2015). "We review herein the current understanding on the actions of leptin in the lung, and summarize the recent advances on its role in the pathophysiology of respiratory diseases." (PMID 21040518, 2010). "Over the past years, extensive research has been conducted concerning the impact of leptin on various respiratory disorders." (PMID 21040518, 2010). "The boundary from research to clinical application is far from being crossed, as the current data have not revealed an exact role for leptin in the diagnosis, management or follow-up of patients with diseases of the respiratory system." (PMID 21040518, 2010).
neurodevelopmental disorder (7 papers, 2019 to 2024). A behavioral and cognitive disorder with onset during the developmental period that involves impaired or aberrant development of intellectual, motor, or social functions. "Recent studies have emphasized the importance of leptin and its receptor in neurological conditions and neurodevelopmental disorders." (PMID 39273520, 2024). "Any dysregulation in fetal leptin levels leads to mental health impairments and neurodevelopmental disorders, including ASD." (PMID 33092575, 2020). "The brain leptin-glutamate or leptin-serotonin interactions have been proposed as possible mechanisms involved in the development of neurodevelopmental disorders, including ASD." (PMID 33092575, 2020). "Leptin dysregulation has been proposed as a mechanism of psychopathology associated with mental health disorders, and elevated circulating leptin was consistently found in childhood neurodevelopmental disorders including ASD." (PMID 31835709, 2019). "Indeed, elevated levels of circulating leptin are consistently found in neurodevelopmental disorders including ASD." (PMID 36290713, 2022). "Although translating animal research to the human situation is difficult, the developmental window of the actions of elevated leptin levels on GABAergic inhibition in vivo and in vitro is consistent with a possible role of elevated leptin levels in neurodevelopmental disorders." (PMID 33183317, 2020).
brain disorder (5 papers, 2018 to 2024). A disease affecting the brain or part of the brain. "Potential therapeutic strategies, including leptin sensitizers, show promise in mitigating brain disorders associated with leptin resistance." (PMID 39594988, 2024). "It is therefore tempting to speculate that leptin signaling may also play a role in brain diseases with an inflammatory component, perhaps via the regulation of the perivascular coverage and leukocyte infiltration." (PMID 29410615, 2018). "Furthermore, leptin has been reported to be neuroprotective in numerous brain diseases." (PMID 29410615, 2018). "It is suggested that changes in leptin are independent of circadian rhythms and stress factors; however, the endogenous modulation of leptin might be essential in preventing various chronic metabolic and brain diseases." (PMID 34884416, 2021).
retinopathy (5 papers, 2016 to 2025). "In this study, we characterized the retinal vascular changes caused by DMT1 retinopathy in NOD mice and DMT2 retinopathy in db/db leptin-deficient mice." (PMID 36613769, 2022).
hematologic malignancies (4 papers, 2022 to 2023). "Leptin serum levels prior to conditioning were determined in a cohort of patients transplanted for various hematologic malignancies (n = 524) and correlated retrospectively with clinical outcome." (PMID 35216457, 2022).
vasculopathy (4 papers, 2007 to 2023). "In addition, we previously reported that higher levels of serum leptin are closely associated with pre-existing vasculopathy and resultant higher rate of AVF maturation failure in HD patients." (PMID 32123226, 2020). "However, in an earlier study, we found that higher serum leptin levels were closely associated with pre-existing vasculopathy and concomitant higher rates of AVF maturation failure in HD patients." (PMID 32123226, 2020). "Taken together, these clinical data point out considerable incongruity about the role of leptin in vasculopathy." (PMID 34064112, 2021). "In fact, it is now clear that leptin influences a variety of physiological and pathological processes including angiogenesis and vascular disorders." (PMID 17425777, 2007).
benign tumors (3 papers, 2009 to 2025). "Although leptin’s expression is common in most OC cells and is associated with higher aggressiveness and poorer treatment outcome, circulating leptin levels are usually lower in presence of OC compared to benign tumors, as could also be observed in our setting." (PMID 35406551, 2022). "A multivariate model including five proteins (CA125, osteopontin, HE4, leptin, and PRL) was found to have an AUC value of 0.996, outperforming CA125 alone; however, only 25 patients with benign tumors and 18 patients with OC were analyzed in this study." (PMID 40502685, 2025).
digestive diseases (3 papers, 2020 to 2025). "Considering the current review, almost all digestive diseases are associated with altered adipokine profiles; with few exceptions, the unfavorable and favorable implications of leptin and adiponectin, respectively, have been consistently reported." (PMID 33167521, 2020). "Taken together, our findings implicate leptin/LepRb as an important target of PF and identify it as a potential biomarker for human patients with gastrointestinal disorders." (PMID 36225193, 2022). "Notably, leptin (LEP), GDF15, and ADM showed the strongest associations with lung function, while BST2, THBS2, and CEACAM1 exhibited the most significant associations with digestive diseases." (PMID 40048323, 2025). "However, the exact role of leptin in a rat model with a gastrointestinal disorder, specifically induced via complex stimulation of EPSD, TNBS, and chronic unpredictable mild stress (CUMS), is unknown." (PMID 36225193, 2022).
musculoskeletal diseases (2 papers, 2018 to 2022). "Furthermore, studies were largely being limited to leptin with little work evaluating other adipokines (adiponectin, resistin, adipsin, etc.)that are now actively being investigated in other musculoskeletal diseases." (PMID 29695079, 2018).
blood cancer (1 paper, 2025). "Besides, high levels of leptin in concert with low adiponectin can increase the risk of blood cancer occurrence." (PMID 40248695, 2025).
bone disorder (1 paper, 2024). "Our findings suggest a significant role for dysregulated leptin signalling in INC‐related bone disorder, either directly or potentially involving a muscle‐bone interplay." (PMID 39210624, 2024).
LEP also shares sentences with these, for which no sentence is quoted: acute myocardial infarction (16 papers); Overweight (10); chronic periodontitis (9); end-stage renal disease (8); essential hypertension (7); hypertrophy (7); stable angina (6); Adult onset (5); peripheral neuropathy (5); alcoholic cirrhosis (4); chronic bronchitis (4); idiopathic pulmonary fibrosis (4); multiple myeloma (4); Onset (4); pulmonary hypertension (4); spinal cord injury (4); systemic inflammatory response syndrome (4); Ventricular hypertrophy (4); adrenal adenoma (3); age (3); binge eating disorder (3); childhood cancer (3); ciliopathies (3); diabetic ketoacidosis (3); dialysis (3); endometrial tumor (3); growth deficiency (3); hand osteoarthritis (3); hyperhomocysteinemia (3); Hypoalbuminemia (3).
A further 287 diseases each share a sentence with LEP in 3 papers or fewer.